INS (insulin)
Diseases named in the same sentence as INS in open-access papers (continued):
Sharing a sentence is not in itself a finding about the gene and the disease.
Insulin resistance (continued). "Taken together, those results suggested that the pathogenesis of GDM may be similar to type II diabetes, characterized with excessive insulin secretion and insulin resistance, and DNA methylation plays an important role in the process." (PMID 35606885, 2022). "MS risk decreases have been recorded with as little as 30 min of moderate-intensity activity per day, and the process involves numerous pathways, including body mass regulation, hypertension, insulin resistance reduction, dyslipidemia, insulin sensitivity enhancement, and glycemic control." (PMID 35185617, 2022). "Our results suggest that the compound can specifically inhibit PTP1B in vivo and might have the ability to improve insulin resistance and insulin secretion." (PMID 36875821, 2022). "They found that whereas the insulin secretion score had a stronger association with T2D in leaner individuals, the role of polygenic insulin resistance was independent of body size." (PMID 36614099, 2022). "Different mechanisms might contribute to the dysregulation of the insulin signaling pathway, but many insulin resistance inducers activate IRS kinases targeting the IRS-1 protein." (PMID 35327570, 2022). "Considering that insulin resistance and insulin secretion capacity were defined on the basis of the median values within this group, the definition may change depending on the population." (PMID 35672344, 2022). "All traditional cardiovascular and metabolic risk factors (age, male sex, lipid profile, fasting glucose, insulin, homeostatic model assessment of insulin resistance [HOMA-IR], blood pressure, and smoking) were more adversely affected in participants with NAFLD than in those without NAFLD." (PMID 35382785, 2022). "Patients with DM can suffer compromised synovium function, as the development of synovial insulin resistance under hyperglycemic conditions reduces the ability of insulin to regulate glucose levels and suppress the production of inflammatory mediators known to stimulate the progression of OA." (PMID 35265601, 2022). "Third, the high levels of circulating free fatty acids could lead to lipotoxicity and promote myocardial insulin resistance through an inhibition of glucose oxidation and insulin signaling in the failing heart." (PMID 35405935, 2022). "Low SMM reduces insulin-mediated glucose disposal and promotes insulin resistance." (PMID 35558748, 2022). "On the other hand, insulin induces vasodilation through NO synthesis, and evidence indicates that insulin resistance in the endothelium could link MS and hypertension." (PMID 35651975, 2022). "The difference in the treatment responses could be ascribed to a different lower insulin secretory function and less insulin resistance in T2DM or the different genetics in these populations." (PMID 36314019, 2022). "The BBR-BSA NPs-treated rats (T-BBR-BSA NPs) significantly (P < 0.05) reduced the hyperglycemia and the peripheral insulin resistance features and elevated the insulin sensitivity and β-cell function (HOMA-β) compared to the stressed rats, BBR-, BSA NPs-, and Ator- treated rats." (PMID 36261663, 2022). "Insulin dysregulation may be manifested by hyperinsulinemia; hyperglycemia; hypertriglyceridemia; and insulin resistance." (PMID 35873691, 2022). "In addition, previous studies found that resistin was weakly correlated with other inflammatory molecules such as TNF-α, IL-6, insulin, and insulin resistance measured by homeostasis model assessment-insulin resistance (HOMA-IR)." (PMID 36428592, 2022). "From a molecular point of view, it is reasonable to believe that IL-17 may be able to induce insulin resistance by acting on insulin signaling pathways." (PMID 36012327, 2022). "However, a marginal reduction in visceral adipose tissue (VAT), fasting insulin (FI), and homeostatic model assessment of insulin resistance (HOMA IR) was noted." (PMID 35453317, 2022).
Insulin resistance (continued). "The outcomes indicated that the use of NG-In might be a promising new approach to restore cerebral insulin function in insulin resistance conditions." (PMID 35741464, 2022). "In addition, several metabolites of fructose (lactate, FFA, ceramide) contribute to the establishment of insulin resistance and the increase of insulin, in turn, promotes the deposition of adipose tissue." (PMID 35492316, 2022). "Type-2 diabetic patients show increased inflammatory cytokines and autoimmune responses in the pancreatic islet cells and can cause insulin resistance and decreased insulin secretion, although the whole mechanism is not yet clearly understood." (PMID 35057501, 2022). "Inflammatory cytokines such as TNFα also reduce insulin function and facilitate insulin resistance." (PMID 35462993, 2022). "As observed in animal models, hyperglycemia, accompanied by obesity and insulin resistance, initially induces β-cell compensatory responses to increase insulin synthesis and secretion as well as promote β-cell proliferation and hypertrophy to increase β-cell mass." (PMID 35929791, 2022). "Insulin homeostasis is important to regulate the lipolysis, but insulin resistance could disrupt and impair the lipolysis in subjects with T2DM." (PMID 35431907, 2022). "Mendelian randomization studies were inconsistent for the causality, one supporting an adiponectin causal relationship to insulin sensitivity, another not supporting causation of insulin resistance or type 2 diabetes." (PMID 36355169, 2022). "Elevated level of protein carbonylation in dexamethasone-treated (by 110%) and in TNF-α-treated (by 50%) adipocytes reflected cumulative oxidative stress in insulin-resistant cells and pointed that the increase in ROS level precedes and triggers the onset of detectable insulin resistance." (PMID 36246880, 2022). "We described that miR-7, which is itself regulated by insulin, impairs insulin signaling and could lead to insulin resistance in the brain through the post-transcriptional regulation INSR, IRS-2." (PMID 36010613, 2022). "However, insulin resistance destroys insulin signalling transduction in SCs, depleting important myelin lipid components and eventually leading to demyelination, while acylcarnitine accumulation further aggravates axon loss." (PMID 35224109, 2022). "Our results showed that the intake of HFD increased insulin levels, insulin resistance, and length." (PMID 35215391, 2022). "Likewise, low-grade chronic inflammation associated with obesity and the subsequent increase in pro-inflammatory cytokine secretion is associated with insulin resistance, with TNF-α, IL-1β, and IL-6 directly impairing insulin signal transduction." (PMID 35883605, 2022). "Another study suggested that infliximab may have beneficial effects on insulin sensitivity in RA and AS patients with a high degree of insulin resistance at baseline." (PMID 35629988, 2022). "A state of maternal insulin resistance might drive insulin receptor abundance on vascular endothelial cells leading to insulin activation of the MAPK pathways and secretion of endothelin leading to vasoconstriction." (PMID 35258482, 2022). "Obesity is nowadays the most prevalent chronic disease among children and adolescents, which can be often accompanied by different comorbidities related to abnormal insulin-mediated glucose control (e.g., insulin resistance, impaired fasting glucose, impaired glucose tolerance) and dyslipidemia." (PMID 36711380, 2022). "It seems that defects in insulin-induced glucose transport in skeletal muscles might be responsible for the induction of insulin resistance (Goldstein, 2002 ▶)." (PMID 35145895, 2022). "Similarly, an animal study demonstrated that replacement of lard by MCT in a high-fat diet ameliorated changes to fasting blood glucose, insulin, and insulin resistance." (PMID 35223950, 2022). "The pancreas attempts to overcome insulin resistance by increasing insulin secretion." (PMID 35562979, 2022).
Insulin resistance (continued). "Altogether, it is concluded that the altered secretions of four adipokines, adiponectin, leptin, visfatin and chemerin, may contribute to the defective production/action of insulin and, concomitantly, insulin resistance." (PMID 35629157, 2022). "Hepatic insulin resistance is characterized by insufficient insulin sensitivity or impaired insulin signaling in the liver, which increases inappropriate gluconeogenesis and glucose output, consequently developing hyperglycemia and impeding whole-body energy utilization." (PMID 35328400, 2022). "Moreover, this is further corroborated by the fact that the insulin assay is higher in subjects than in controls, signifying insulin resistance in T2DM." (PMID 36340870, 2022). "TXNIP is a mediator of insulin resistance in the liver, skeletal muscle, and adipose tissue and impaired pancreatic beta-cell insulin secretion and TNFα decreases insulin receptor signaling in adipose tissue and skeletal muscle, particularly prior to the development of T2DM." (PMID 35269594, 2022). "Although the molecular mechanism by which lipid causes insulin resistance is not fully elucidated, numerous experimental and clinical studies have shown a close correlation between insulin sensitivity and ectopic lipid storage in the muscle and liver." (PMID 36099304, 2022). "In the context of insulin resistance, an unanswered question is whether different insulin target tissues have different sensitivity to arsenic exposure." (PMID 35651975, 2022). "Therefore we chose 8 months of age to test the insulin signaling pathway, and we show that low level of expression of PH-Tau is enough to induce brain insulin resistance." (PMID 35264925, 2022). "Remarkably, MK hindered the insulin-stimulated translocation of the glucose transporter GLUT4 to the surface of adipocytes and activated the STAT3-suppressor of cytokine signaling 3 pathway, implicated in adipocyte insulin resistance." (PMID 36204583, 2022). "Previous studies have revealed that MOTS-c levels are associated with IR and obesity markers including body mass index (BMI), waist circumference, waist-to-hip ratio, fasting insulin level, Homeostatic Model Assessment for Insulin Resistance (HOMA-IR), and HbA1c." (PMID 35989823, 2022). "Notably, it has been demonstrated to restore insulin sensitivity in animal models of insulin resistance, as summarized by Lee and Kim." (PMID 36038539, 2022). "It is well known that liver fibrosis can lead to the development of insulin resistance (IR), as liver steatosis may interfere with the function of hepatocytes, particularly their ability to respond to changes in insulin levels leading to the development of IR." (PMID 36211651, 2022). "Myriocin treatment or Sptlc2 knockdown in these cells abolished the inhibition of insulin sensitivity, indicating that ceramides produced through de novo synthesis have critical roles in the manifestation of neuronal insulin resistance during fatty acid excess." (PMID 35789435, 2022). "Insulin resistance of the alpha-cell was proposed to impair the inhibition of glucagon secretion by insulin and may thereby increase GCGN levels." (PMID 35662921, 2022). "Insulin dysregulation mainly includes hyperinsulinemia and insulin resistance." (PMID 36501200, 2022). "The study also suggested that persistently low salt intake might increase fasting insulin and subsequently increase insulin resistance." (PMID 35784580, 2022). "Indeed, transcription factors such as FoxO1 and SREBP1 have been identified as regulators of insulin action and participants in the progression of insulin resistance via their control of the expression of specific genes in glucogenic and lipogenic pathways." (PMID 35440636, 2022). "Furthermore, CM fruit extracts not only increased glucose uptake rate in the tested cells but were also able to reverse previously developed insulin resistance and restore proper insulin signaling." (PMID 35684107, 2022).
Insulin resistance (continued). "In addition, there is a failure of the usual cellular response to insulin (insulin resistance), which occurs in the perioperative period." (PMID 35405902, 2022). "In addition to modifications of insulin secretion, adult SL offspring exhibit changes in peripheral insulin signaling, suggestive of insulin resistance." (PMID 35631188, 2022). "Additionally, an upregulated expression of the pro-inflammatory gene Angptl4, which is supposed to increase insulin resistance, was observed; on the other hand, Irs1, a gene that improves insulin sensitivity, was downregulated." (PMID 36299624, 2022). "Several studies have reported that non-insulin-based indices of insulin resistance could be useful tools for the early detection of insulin resistance." (PMID 36613109, 2022). "Insulin resistance (IR) refers to a reduced biological effectiveness of insulin on effector organs." (PMID 36589794, 2022). "M. charantia active components could reduce oxidative stress, decrease insulin resistance, increase insulin release, reduce adiposity, modulate glycolysis and gluconeogenesis, as well as lower oxidative status." (PMID 35408574, 2022). "Injection of exosomes derived from ATMs of obese mice into lean mice leads to increased glucose tolerance, insulin resistance, and glucose-stimulated insulin secretion, which may be mediated by the transfer of microRNAs that regulate insulin sensitivity." (PMID 36012516, 2022). "The utility of using fasting insulin for the diagnosis of insulin resistance continues to be debated, as fasting alone may put horses into an insulin-resistant state." (PMID 35873691, 2022). "Moreover, XBP1-s inhibits the secretion of pro-inflammatory adipokines by increasing insulin signal transduction and adiponectin secretion, and by eliminating palmitate-induced adipocyte insulin resistance." (PMID 35269888, 2022). "Moreover, increased glucocorticoid and activation of cortisol from cortisone exacerbates metabolic stress, including obesity, suppresses insulin secretion, induces insulin resistance, and reduces peripheral glucose uptake." (PMID 35276788, 2022). "Evaluation of insulin resistance can be challenging as changes in insulin sensitivity may be related to tissue- or organ-specific differences." (PMID 36295850, 2022). "Prolonged fasting can attenuate the β-cell’s secretory capacity by limiting insulin production and increasing insulin turnover to prevent hypoglycemia, whereas the expansion of ER and Golgi membranes seems to be a common adaptation to insulin resistance and episodic hyperglycemia." (PMID 35204835, 2022). "These patterns confirmed that the deficient insulin secretion rather than the insulin resistance, often called into play, was the driver of young-onset T2D in India, in contrast to obesity and insulin resistance in young Swedish and Finnish T2D populations." (PMID 36614099, 2022). "However, if insulin resistance persists, insulin secretion appears to decrease again and insulin needs cannot be supplied." (PMID 35216514, 2022). "Intensive insulin therapy, nevertheless, is essential for clinical management of women with type 1 diabetes (T1D) who are insulin sensitive, and for women with T2D who have pronounced insulin resistance." (PMID 35269778, 2022). "Impairment in the insulin signaling cascade has been suggested to result in insulin resistance." (PMID 35238495, 2022). "When the body is obese, macrophages, neutrophils, and other immune cells reside or infiltrate metabolic organs, causing chronic inflammation and metabolic disorders, thus decreasing insulin sensitivity and leading to the occurrence of insulin resistance (IR) and T2DM." (PMID 36676939, 2022). "For example, if high levels of glucose or HbA1c tend to appear in parallel to high levels of insulin, insulin resistance may be present." (PMID 35931735, 2022).
Insulin resistance (continued). "In another study, Cr3 administered at the same dosages (1 and 5 mg Cr/kg BW) did not affect blood glucose and lipid levels, but decreased serum insulin concentration and improved insulin resistance indices (HOMA-IR, HOMA-B) in Wistar rats fed a high-fructose diet." (PMID 36297315, 2022). "Consistently, RABGGTA knockdown‐mediated GGTase II inhibition in skeletal muscle caused insulin resistance without disturbing insulin signalling in vivo." (PMID 35961942, 2022). "Supplementation with the higher dose of vitamin D (50,000 IU) had a significant effect in improving the serum levels of vitamin D. Supplementation with the high dose of vitamin D ameliorated insulin resistance and had a positive effect on improving insulin sensitivity in overweight females." (PMID 36362806, 2022). "Some studies have considered that high physiological levels of exogenous insulin and hyperglycemia could be responsible for insulin resistance in T1D patients." (PMID 36619558, 2022). "The addition of insulin, which usually acts as a vasodilatory agent, did not increase MBV or MBF compared with GLP-1 alone, which suggests the presence of microvascular insulin resistance and the insulin-independent effects of GLP-1 on cardiac microvasculature." (PMID 35370744, 2022). "Pathophysiologically, the development of T2DM is currently understood as a continuous process with multiple steps ranging from elevated insulin secretion under euglycaemic conditions, followed by increased insulin resistance, decreasing β-cell mass, and breakdown of the gluco-homeostasis." (PMID 34169342, 2022). "The hypothesis that neurons, like other tissues in diabetes, develop insulin resistance has also been postulated, although little is known about insulin signalling in the peripheral nervous system, making mechanistic investigations difficult." (PMID 35631433, 2022). "Similarly, mouse models of menopause exhibit weight gain, elevated fasting insulin, and insulin resistance." (PMID 36315375, 2022). "However, in obese adipose tissue, macrophages are polarized to the pro-inflammatory M1 type; these changes induce the production of pro-inflammatory factors, which impairs insulin signaling and promotes insulin resistance." (PMID 36517050, 2022). "T2DM primarily occurs because of defects in insulin secretion and insulin resistance." (PMID 36510177, 2022). "With insulin resistance constituting an independent predictor of endothelial dysfunction in individuals without classical risk factors for atherosclerosis, insulin sensitizers are increasingly being considered as a promising preventive approach." (PMID 35457157, 2022). "Although the pathogenesis of GDM is still unknown, two contributing factors have been involved in its progression: β-cell dysfunction and alterations in insulin secretion to compensate for insulin resistance induced by pregnancy." (PMID 35813659, 2022). "Further, we sought to determine whether changes in related measures [haemoglobin A1C (HbA1C), fasting plasma glucose, insulin, Homeostatic Model Assessment of Insulin Resistance (HOMA-IR)] were concordant with any observed effect." (PMID 35441656, 2022). "Studies have shown that obesity and insulin resistance are directly related to the activation or overexpression of delta-9–18 desaturase activity since delta-9–18 desaturase activity is increased by dietary glucose, fructose, and insulin." (PMID 35898714, 2022). "Mechanistically, POPs can alter the insulin-stimulated glucose transporter GLUT4, impair insulin signaling pathways, disrupt mitochondrial function, and promote chronic-low grade inflammation, thereby contributing to insulin resistance." (PMID 35303528, 2022). "Moreover, SHBG showed a negative correlation with several parameters such as blood pressure, body mass index, waist circumference, insulin, and the homeostatic model assessment of insulin resistance (HOMA-IR)." (PMID 36421197, 2022).